ENSG00000270249 (novel protein)
Gene: Protein-coding gene on chromosome 7 (102,541,501 to 102,592,444, reverse strand). Ensembl gene ENSG00000270249.
Genetic constraint (gnomAD): Loss-of-function variants: 0 observed, 1.74 expected, observed/expected ratio (o/e) 0, 90% interval 0 to 1.46. That is too few expected variants to judge how well the gene tolerates losing a copy. Missense variants: 0 observed, 29.16 expected, observed/expected ratio (o/e) 0, 90% interval 0 to 0.1. Synonymous variants: 0 observed, 8.37 expected, observed/expected ratio (o/e) 0, 90% interval 0 to 0.36.